Y_RNA (Y RNA )
Gene: Miscellaneous RNA gene on chromosome 2 (182,828,124 to 182,828,221, forward strand). Ensembl gene ENSG00000212404.
Homologues: Orthologues: macaque Y_RNA (92% identical). Paralogues in human: Y_RNA (86% identical), Y_RNA (85% identical), RNY3 (84% identical), Y_RNA (84% identical), Y_RNA (83% identical), Y_RNA (82% identical), RNY3P1 (81% identical), RNY3P14 (81% identical), Y_RNA (81% identical), Y_RNA (80% identical), RNY3P13 (79% identical), Y_RNA (79% identical), and 95 more.